CRP (C-reactive protein)
Diseases named in the same sentence as CRP in open-access papers (continued):
Sharing a sentence is not in itself a finding about the gene and the disease.
acute pancreatitis (continued). "Therefore, serum CRP, and BAFF at day of admission were included to generate a model that would discriminate between severe and less severe courses of acute pancreatitis." (PMID 23342125, 2013). "Additionally, this approach gave us the opportunity to evaluate BAFF as compared to CRP, IL-6, PCT, and number of leucocytes as a predictor of severity and course of acute pancreatitis." (PMID 23342125, 2013). "C-reactive protein (CRP) that is synthesized by the hepatocytes is a nonspecific inflammatory marker routinely used in assessment of severity of acute pancreatitis." (PMID 20130823, 2009). "However, while circRNAs hold promise as diagnostic biomarkers for AP, they should be evaluated against established diagnostic markers such as amylase, lipase, C-reactive protein (CRP), and clinical scoring systems like BISAP (Bedside Index for Severity in Acute Pancreatitis) and Ranson scores." (PMID 41367614, 2025). "However, later studies found that CRP measured at the first visit is not a reliable prognostic marker for human acute pancreatitis because CRP peak levels are reached only after 48–72 h." (PMID 34256804, 2021). "In addition, in acute pancreatitis, inflammatory markers such as C-Reactive Protein (CRP) and procalcitonin; although not included in the scoring systems, their relationships with important prognostic markers such as organ failure and infected necrosis have been examined in many studies." (PMID 40342330, 2025). "Although the total WBC count is a component of numerous grading systems for pancreatitis, unlike CRP or blood urea nitrogen, the total WBC count is not evaluated as an independent marker for predicting the outcome of acute pancreatitis." (PMID 36340538, 2022). "AP, acute pancreatitis; BISAP, Bedside Index of Severity in Acute Pancreatitis; CI, confidence interval; CRP, C-reactive protein; PPV, positive predictive value; NPV, negative predictive value; ACC, accuracy." (PMID 31114724, 2019). "However, in our study, we did not analyze CRP and PCT values, as they are not routinely measured in cases of acute pancreatitis at our hospital." (PMID 40429414, 2025).
cognitive decline (177 papers, 2011 to 2026). "Here, we report comparable results for DNAm CRP and highlight that an elevated DNAm CRP score is also consistently associated with subsequent cognitive decline and brain volume loss." (PMID 41274863, 2025). "Increased levels of C-reactive protein (CRP) and other inflammatory markers are associated with more severe psychosis and cognitive decline." (PMID 40242178, 2025). "In fact, increased BMI is related to the elevation of inflammatory proteins only in women, including C-reactive protein and interleukin-6, which can cause rapid cognitive decline due to an active inflammatory condition." (PMID 40114234, 2025). "Elevated levels of inflammatory markers (e.g., CRP, interleukin-6 (IL-6), tumor necrosis factors) are related to cognitive decline and increased risk of AD/ADRD, found both in the peripheral blood and cerebral spinal fluid (CSF)." (PMID 41440093, 2025). "Elevated CRP levels are associated with atherosclerosis and other vascular conditions that can impair cerebral blood flow, leading to cognitive decline." (PMID 39913250, 2025). "Among them, levels of chronic inflammatory factors such as CRP and IL-6 are associated with cognitive decline." (PMID 40809769, 2025). "Inflammation appeared to play a prominent role, with several studies demonstrating that higher levels of inflammatory markers, such as CRP and interleukin-6, were linked to both social adversity and cognitive decline." (PMID 41278514, 2025). "Detectable association of CRP smaller left medial temporal lobes as buttress verbal episodic memory consolidation hinted that LGI was related to cognitive decline." (PMID 39064755, 2024). "As an acute phase reactant whose level rises with inflammation, an elevated level of fibrinogen, along with CRP, has been linked to faster cognitive decline in older adults as well." (PMID 41542283, 2024). "Indicative of the importance of inflammation during aging, higher CRP levels in aged individuals are strongly associated with a faster rate of cognitive decline over an 8-year period and greater risk of impairment in Activities of Daily Living (ADL)." (PMID 37298603, 2023). "Other proinflammatory factors, such as homocysteine and interleukin-6 (IL-6), C-reactive protein (CRP), and alpha-1-antimotrypsin, have been associated with neuroinflammation and cognitive decline." (PMID 36983685, 2023). "An observational study of over 5000 participants found higher levels of IL-6 and CRP to be associated with worse cognitive function and steeper cognitive decline." (PMID 37178386, 2023). "Clinical studies showed that elevated CRP levels increased the risk of both developing AD and of cognitive decline in various populations." (PMID 36981618, 2023). "More specifically, several studies showed elevated levels of IL-6 and CRP to be associated with global cognitive decline and lower performance in executive functions and memory." (PMID 37168718, 2023). "Specifically, increased CRP concentration at baseline was associated with slower cognitive decline in patients with AD." (PMID 37593375, 2023). "This is in line with previous studies in adults over the age of 75 that found that increased CRP predicts better memory performance and decreased risk for cognitive decline." (PMID 39081969, 2023). "In this sense, the present study shows that average inflammatory activity measured using C-reactive protein throughout follow-up was associated with cognitive decline in patients with JIA." (PMID 35885032, 2022). "In the context of cognitive decline, sICAM-1 and CRP have previously been associated with AD pathology." (PMID 35643540, 2022). "Based on our evaluation of various inflammatory parameters, we found a stronger association between cognitive decline and C-reactive protein than with clinical activity indexes such as JADAS27." (PMID 35885032, 2022).
cognitive decline (continued). "Although previous findings have supported CRP as a risk factor for cognitive decline, CRP has shown only a marginal association with global cognitive decline in prior longitudinal research." (PMID 35753000, 2022). "A strong association between the elevation of plasma CRP and longitudinal cognitive decline has been detected, largely among older individuals." (PMID 33869072, 2021). "In the Rotterdam Study, elevated levels of pro-inflammatory cytokines including IL-6 and CRP were found to be associated with cognitive decline and executive function." (PMID 32455946, 2020). "Our objective was to examine the association of baseline C-reaction protein (CRP) with cognitive decline among a large racially diverse cohort of older adults." (PMID 33382815, 2020). "Third, LPA or general activity is associated with lower levels of the plasma inflammatory marker c-reactive protein, a hallmark of systemic inflammation, often associated with cognitive decline." (PMID 32321436, 2020). "For instance, a recent study found an association between midlife CRP and 20-year cognitive decline that was robust to adjustment for multiple covariates." (PMID 33382815, 2020). "Firstly, the cross-sectional design limits the possibility to draw conclusions about the association of CRP levels with cognitive decline over time." (PMID 32994460, 2020). "Elevated levels of inflammatory markers (i.e., C-reactive protein (CRP), interleukin-6, IL-1 receptor antagonist) are associated with reduced physical performance as well as cognitive decline in older adults." (PMID 28699886, 2017). "Studies with older population samples show that higher levels of CRP are associated with cognitive decline, particularly in women." (PMID 28659812, 2017). "Conclusions: this study strengthens previous cross-sectional findings and shows elevated levels of CRP to be linked to a decreased risk of longitudinal cognitive decline in the very old." (PMID 24305621, 2014). "Background: circulating measures of inflammatory markers, such as C-reactive protein (CRP) have been associated with an increased risk of future cognitive decline." (PMID 24305621, 2014). "Elevated levels of CRP and IL-6 reflect an enhanced inflammatory state and are associated with accelerated cognitive decline." (PMID 23308123, 2013). "Investigation of mechanisms linking CRP to cognitive decline in humans is hampered by the inability to distinguish cause from effect in conventional association studies." (PMID 21915265, 2011). "These two aspects together substantially lessen support for CRP as causal agent in cognitive decline and as a consequence suggest a need for new thinking in this area of research." (PMID 21915265, 2011). "We report here an association of concentrations of CRP with cognitive performance at baseline, and with an increased rate of cognitive decline during follow-up, at least in one cognitive domain." (PMID 21915265, 2011). "Second, this is the largest study we are aware to study the association of CRP genotypes with cognitive decline." (PMID 21915265, 2011). "This approach is more robust to detect cognitive decline than cross-sectional association studies of CRP with cognition, as the latter studies are more vulnerable to confounding and individual variance in test performance." (PMID 21915265, 2011). "Plasma concentrations of C-reactive protein (CRP), a marker of chronic inflammation, have been associated with numerous clinical conditions, including cognitive decline in old age." (PMID 21915265, 2011). "Interestingly, higher concentrations of CRP are associated with a slowing of cognitive decline in patients diagnosed with AD." (PMID 39807297, 2025). "Inadequate vitamin E intake has been associated with the loss of muscle strength and cognitive decline, which are features of frailty syndrome, and improvements in C-reactive protein and IL-6 levels have been observed in frail older adults with vitamin E supplementation." (PMID 41305625, 2025).
cognitive decline (continued). "Furthermore, longitudinal studies have demonstrated that elevated baseline CRP is associated with an increased risk of cognitive decline and AD development, potentially through sustained IL-6-mediated inflammatory signaling and vascular injury pathways." (PMID 41373439, 2025). "In addition, exercise has anti-inflammatory effects by reducing systemic inflammation, which is associated with cognitive decline, and lowering levels of C-reactive protein (CRP) and interleukin-6 (IL-6)." (PMID 39651037, 2024). "Inflammatory markers, including CRP, interleukins, and tumor necrosis factor, were associated with neuroinflammatory processes, which can exacerbate synaptic dysfunction, promote neuronal injury, and contribute to cognitive decline." (PMID 39592894, 2024). "Systemic levels of interleukin (IL)-6 and C-reactive protein (CRP), two inflammatory markers extensively explored in epidemiological studies on aging, were associated with physical and cognitive decline in a representative sample of 415 community-dwelling older adults enrolled in the BELFRAIL study." (PMID 38337499, 2024). "Thus, it appears that one factor on the pathway to healthy longevity is for aged individuals to maintain or achieve low plasma CRP levels (low peripheral inflammation) to reduce risk of cognitive decline, ADL impairment, and mortality itself." (PMID 37298603, 2023). "CRP serves as a biomarker for general inflammation, and emerging evidence indicates that changes in CRP expression may be associated with cognitive decline in neurodegenerative diseases." (PMID 37509012, 2023). "Additionally, aside from pathogens, other more distal factors, such as pollution and traumatic events, have been linked to both elevated CRP levels and increased cognitive decline." (PMID 39081969, 2023). "Thus, elevated levels of C-reactive protein were associated with a reduced risk of longitudinal cognitive decline in older adults." (PMID 37686198, 2023). "For example, elevated serum CRP-levels were associated with cognitive decline in elderly women, and serum levels of CRP, Interleukin-6 and Interleukin-10 were negatively associated with a composite score of executive function and processing speed, but not with verbal episodic memory." (PMID 37467176, 2023). "In addition, plasma IgA levels were associated with cognitive decline, CRP, Aβ pathology, and brain IgA immunoreactivity in APOEε4 non-carriers." (PMID 36008818, 2022). "In addition, previous longitudinal studies have confirmed a significant association between CRP levels and cognitive decline, affirming how underlying inflammation (using CRP as a marker) likely affects an individual’s cognitive functioning in the long run." (PMID 34362224, 2021). "First, prior studies among older adults that reported an association between CRP and cognitive decline have largely used brief cognitive screeners (i.e., Mini-Mental State Examination), defined cognitive decline based on a single follow-up, or had brief follow-up periods (≤ 10 years)." (PMID 33382815, 2020). "Moreover, immune status can also influence brain function in humans as the Hoorn Study evidenced that increased levels of inflammatory plasma markers (TNF-α, IL-6, IL-8, C-reactive protein) were associated with cognitive decline." (PMID 28638339, 2017). "Findings indicated that participants in the highest tertile of IL-6 or CRP serum concentrations performed significantly worse at baseline and follow-up 3MS, with a 24% increase in risk of cognitive decline over the two year period in comparison to those participants in the lowest tertile." (PMID 25793613, 2015). "In another large-scale, prospective occupational cohort study over 10 years, increased levels of inflammatory markers, both CRP and IL-6 at midlife, were moderately associated with a lower cognitive status but were only slightly associated with cognitive decline." (PMID 26682220, 2015).
cognitive decline (continued). "Besides larger studies more research is warranted in the ‘upstream’ mechanisms/pathways causing CRP to rise concomitantly with cognitive decline, for example an examination of pro-inflammatory cytokines." (PMID 21915265, 2011). "Of course there may be residual confounding by unmeasured factors which raise CRP and also cause cognitive decline." (PMID 21915265, 2011). "Therefore, CRP seems to be associated with greater age-related cognitive decline." (PMID 35753000, 2022). "Given that CRP is a biomarker of systemic inflammation that is associated with ACEs, and that systemic inflammation has been identified as a potential risk factor for cognitive decline, CRP may be another potential mediator in the ACEs-to-cognitive decline pathway." (PMID 35753000, 2022). "Therefore, we aimed to investigate the association between CVH and cognitive decline, and then to explore cognitive decline according to hs-CRP levels and CVH to determine whether hs-CRP is valuable as a biomarker for early cognitive dysfunction." (PMID 34293257, 2021). "Associations between CRP and cognitive decline may be moderated by race." (PMID 33382815, 2020). "Secondly, elevated CRP levels were associated with greater cognitive decline, which indicates that inflammatory mechanisms may contribute to CI, though it is unclear whether peripheral inflammation is a by-product of neuropathology or whether it directly contributes to cognitive damage." (PMID 31832073, 2019). "We also cannot discount a reverse causal mechanism whereby an increased CRP is contributed to by cognitive decline; cognitive decline is associated with a poor nutritional status and increase in incident diseases, which in turn could lead to an increased plasma CRP concentration." (PMID 21915265, 2011). "Subjects in the highest tertiles for IL-6 and CRP performed significantly worse on cognitive tests at follow-up than those in the lowest and had higher odds of cognitive decline over two years." (PMID 40805992, 2025). "First, the accumulation of inflammation throughout the body mediates both cognitive decline and muscle atrophy, including C-reactive protein and interleukin-6." (PMID 40576140, 2025). "High circulating levels of inflammatory markers like CRP are indicators of chronic inflammation, which is thought to contribute to the cascade of events leading to neuronal damage and cognitive decline." (PMID 39913250, 2025). "While these findings are not directly comparable to ours due to differences in study design, they highlight CRP as a potential inflammatory marker in LLD and its association with cognitive decline." (PMID 39922907, 2025). "Elevated levels of inflammatory markers, such as C-reactive protein (CRP) and interleukin-6 (IL-6), have been linked to cognitive decline in antidepressant users." (PMID 39377784, 2025). "Beyond being a marker of inflammation, CRP is involved in amyloid plaque formation, vascular injury, and cognitive decline." (PMID 40943152, 2025). "In another follow-up study lasting 10 years, it was shown that there is a significant correlation between CRP concentration and long-term cognitive decline." (PMID 40852521, 2025). "The identification of a CRP threshold that predicts GIC adds clinical value, as it provides a potential biomarker for identifying individuals at high risk for cognitive decline and guiding therapeutic interventions aimed at reducing inflammation." (PMID 41367212, 2025). "Three studies revealed a correlation between high-sensitivity CRP (HS-CRP) levels and cognitive decline in patients with AF, AF patients with cerebral infarction, and elderly individuals with AF." (PMID 39976882, 2025). "Elevated circulating cell‐free DNA (cfDNA) levels in older adults are associated with mortality, inflammation biomarkers (including C‐reactive protein [CRP]), cognitive decline, frailty, and CVD." (PMID 40264357, 2025).